FST (follistatin)
Diseases named in the same sentence as FST in open-access papers (continued):
Sharing a sentence is not in itself a finding about the gene and the disease.
breast carcinoma (25 papers, 2009 to 2025). "Our findings are also in agreement with evidence showing that reduced expression of the Activin A inhibitor Follistatin (FSH) was associated with worse survival of patients with HER2-positive breast cancers and enhanced formation of lung metastases in vivo." (PMID 30805303, 2019). "We found that FST mRNA expressions in breast cancer tissues were significantly low compared with those in normal breast tissues (p< 0.001), suggesting that low FST expression may be a risk factor for BC." (PMID 34001106, 2021). "Validated down-regulated genes include NPC2 involved in the negative regulation of MAPK, TSPAN8 involved in tumor progression and metastasis, ANKRD1 mainly expressed in MDA-MB231 breast cancer cell lines and linked to treatment-resistance in breast cancer, and FST involved in metastasis suppression." (PMID 34680207, 2021). "This is the first report demonstrating that FST expression is reduced in breast cancers compared with normal breast tissue and that elevated FST mRNA is associated with delayed recurrence and survival in patients with breast cancer." (PMID 28583174, 2017). "We found that FST blocks activin-induced breast epithelial cell migration in vitro, suggesting that its loss may promote breast cancer aggressiveness." (PMID 28583174, 2017). "Thus, mice expressing Her2/Neu in the mammary gland provide an ideal model to determine if FST loss is necessary for metastatic progression of cancer by restoring expression of FST in mammary tumors." (PMID 28583174, 2017). "It is possible that resistance to the tumour suppressive actions of activin in breast cancer is linked to the levels of secretion of activin neutralizing molecules such as follistatin, as well as a concurrent decrease in expression of activin type II receptors." (PMID 25884855, 2015). "For example, in mammary carcinoma cells, activin promotes proliferation, while FST reduces tumor growth by enhancing cellular apoptosis." (PMID 38392348, 2024). "Breast cancer is associated with a dramatic downregulation of ADRP and FST along with upregulation of the Serpin, LOX-1, COL1A1, and MIF gene expressions, respectively." (PMID 35138531, 2023). "As expected, several of the genes associated with top differentially methylated probes between these groups have been previously implicated in breast cancer, including SDC2, PBK, ALOX12B, DAG1, ZNF382, and FST." (PMID 35564499, 2022). "For these reasons, differential FST roles are necessary for discerning the heterogeneous natures of breast cancer and its molecular subtypes." (PMID 34001106, 2021). "Some studies reported that serum FST levels were significantly increased in patients with ovarian cancer, hepatocellular cancer, and breast cancer." (PMID 30377409, 2018). "The functional effects of activin and FST on in vitro proliferation, migration, and invasion of breast cancer cells were also examined." (PMID 28583174, 2017). "FST overexpression in an autochthonous mouse model of breast cancer was then used to assess the in vivo impact of FST on metastatic progression." (PMID 28583174, 2017). "In contrast, we used a credentialed and autochthonous model of HER2/Neu-positive breast cancer in which the FST transgene was expressed during the transformation/progression process and likely impacted the mammary microenvironment." (PMID 28583174, 2017). "Examination of multiple breast cancer datasets revealed that FST expression is reduced in breast cancers compared with normal tissue and that low FST expression predicts increased metastasis and reduced overall survival." (PMID 28583174, 2017). "Data reported herein directly show that sustained expression of FST prevents metastatic progression in a mouse model of breast cancer." (PMID 28583174, 2017). "It is also possible that there is discordance between FST mRNA and protein expression in breast cancers." (PMID 28583174, 2017).
breast carcinoma (continued). "As in human breast cancer, we found that FST was profoundly repressed in mammary tumors collected from transgenic mice expressing the Her2/Neu proto-oncogene in the mammary epithelia (MMTV-Neu), as was Fstl3." (PMID 28583174, 2017). "In contrast to BMPs, elevated expression of the activin subunit INHBA predicts worse outcomes in patients with breast cancer and is consistent with our observation that FST prevents metastasis." (PMID 28583174, 2017). "In this study, we show that expression of the activin subunit INHBA is elevated in multiple cohorts of breast cancers, whereas FST is suppressed." (PMID 28583174, 2017). "Kaplan-Meier plots demonstrating the association of high FST expression with recurrence-free survival of luminal A, luminal B, HER2, and basal subtypes of breast cancer." (PMID 28583174, 2017). "Activin is produced by breast cancer cells, inhibiting their proliferation, while follistatin binds to activin and prevents receptor binding with the type II receptor (ActRII), thus promoting proliferation." (PMID 25884855, 2015). "The differential effect of ZOL on follistatin secretion according to ER status of breast cancer cell lines in vitro and in vivo demonstrated in this study, has not been previously reported." (PMID 25884855, 2015). "Activin A inhibits proliferation of both ER-ve and oestrogen positive (ER + ve) breast cancer cells, an effect impaired by follistatin." (PMID 25884855, 2015). "The effects of activin A, its inhibitor follistatin and zoledronic acid on proliferation of breast cancer cells was evaluated using either an MTS proliferation assay or trypan blue." (PMID 25884855, 2015). "Follistatin is a paracrine antagonist of activin and both proteins modify breast cancer cell proliferation." (PMID 25884855, 2015). "We provide the first evidence that ZOL can affect the activin signaling pathway specifically in ER-ve breast cancer cell lines by a dual mechanism; decreasing secretion of follistatin and preventing nuclear localization of linker phosphorylated Smad2." (PMID 25884855, 2015). "Here we show that the EMT-inducer ZEB1 activates the expression of genes, previously associated with breast cancer bone metastasis, including the BMP-inhibitors NOG, FST and CHRDL1." (PMID 25973542, 2015). "Indeed, FST has been described as a good predictor of survival in breast cancer, with high serum FST correlating with better overall and relapse-free survival and low FST levels associated with increased metastasis and reduced survival." (PMID 38392348, 2024). "Furthermore, breast cancer tissues with low FST expression exhibit increased proliferation, migration, and invasion." (PMID 38392348, 2024). "Overexpression of FST in a xenograft breast cancer model was shown to inhibit tumor growth." (PMID 38360876, 2024). "Functional studies showed that activin could increase tumor growth in mammary carcinoma cells, but inhibited angiogenesis in comparison to follistatin-expressed cells." (PMID 34356885, 2021). "It is also notable that activins have well-established morphogen roles during normal development, and that previous work has reported increased INHBA/activin-A activity at the leading edge of HER2-positive breast tumors and that follistatin can suppress HER2-positive breast cancer metastasis." (PMID 34239043, 2021). "Follistatin was identified as one of the bone metastasis signature genes in breast cancer." (PMID 34356885, 2021). "Moreover, expression of FST, the endogenous inhibitor of activin, was downregulated in breast cancer tissue as well as surrounding stroma compared with normal breast tissue." (PMID 28583174, 2017). "The role of FST specifically in breast cancer progression is equally unclear." (PMID 28583174, 2017).
breast carcinoma (continued). "Supporting this possibility, a meta-analysis of 2878 patients with breast cancer (all subtypes) revealed that sustained FST messenger RNA (mRNA) expression correlates with prolonged recurrence-free survival compared with patients whose tumors had low FST expression." (PMID 28583174, 2017). "We assessed whether FST may be a suppressor of tumorigenesis and/or metastatic progression in breast cancer." (PMID 28583174, 2017). "The role of FST in breast disease is mentioned again in a recent study on breast cancer patients." (PMID 27634900, 2016). "The BMP-inhibitors NOG and FST were described to be involved in breast cancer bone metastasis." (PMID 25973542, 2015). "FST mediates the ability of YAP to stimulate cell invasion in melanoma, and its expression correlates with metastasis in a breast cancer mouse model and with survival outcomes in cancer patients." (PMID 38755629, 2024). "Among the genes regulated by Bcl-2 in both melanoma and breast carcinoma models we identified CTGF, CCND3, TEAD2, FST, MYC and TP73." (PMID 38755629, 2024). "The remaining four have all been studied for their effects in the development and maintenance of human breast cancers (TNP1, FST, ANKRD40, TRH)." (PMID 33957863, 2021). "Activin inhibitors, both follistatin and FLRG, were overexpressed in carcinoma compared to that of adjacent normal tissues in breast cancer and hepatocellular carcinoma." (PMID 34356885, 2021). "FST overexpression induces apoptosis of MCF-7 cells and suppresses metastasis in a mouse model of HER2-positive breast cancer." (PMID 34001106, 2021). "The ability of FST to prevent metastatic progression, combined with the propensity for FST to bind and inhibit activin signaling, suggests that activin secreted from the microenvironment may be a key driver of metastatic progression in breast cancer, similarly to TGF-β." (PMID 28583174, 2017). "We focused on those genes that inhibit metastasis in breast cancer including SHARP-1 and the ERα-regulated CCNG2 and the pro-metastatic factor Follistatin." (PMID 26871946, 2016). "This implies that many of the genes specifically increased in bone metastases of breast cancer, e.g. the BMP-inhibitor FST, are dependent on ZEB1 mediated activation." (PMID 25973542, 2015). "Interestingly, the MG signature notably comprised follistatin (FST), a member of the transforming growth factor-β ligands, previously reported as a metastasis suppressor in breast cancer." (PMID 36998085, 2023). "Most important, enforced expression of FST in the mouse mammary gland completely blocks metastases in a model of HER2/Neu-positive breast cancer without having any impact on primary tumor latency or growth." (PMID 28583174, 2017). "Previous analyses of FST expression at the protein level have not demonstrated differential expression between normal breast and breast cancer in small patient cohorts." (PMID 28583174, 2017). "Using publicly available gene expression data, we examined the expression patterns of FST and INHBA, a subunit of activin, in normal and cancerous breast tissue and the prognostic value of FST in breast cancer metastases, recurrence-free survival, and overall survival." (PMID 28583174, 2017). "On the basis of immunohistochemistry (IHC), FST expression did not correlate with disease stage or recurrence in small cohorts of patients with breast cancer." (PMID 28583174, 2017). "Overexpression of FST inhibited growth of subcutaneous mammary carcinoma xenografts, but the impact of FST expression on metastatic progression has not yet been assessed." (PMID 28583174, 2017). "To assess the impact of FST on activin-induced migration of breast epithelial cells, we treated MCF10A and 4T1 cells (a mouse mammary cancer cell line) with activin A in the presence or absence of recombinant FST." (PMID 28583174, 2017).
breast carcinoma (continued). "The clinical neo-adjuvant breast cancer study, ANZAC, evaluated the biological effects of addition of ZOL to first cycle of FEC100 chemotherapy, and showed serum levels of follistatin significantly decreased following administration of ZOL in postmenopausal women." (PMID 25884855, 2015). "To test for the role of BMP-inhibitor expression by the tumor cells in facilitating this differentiation, we additionally incubated Raw264.7 cells with conditioned media (CM) from various breast cancer cells expressing different levels of ZEB1 and the BMP-inhibitors NOG and FST." (PMID 25973542, 2015). "In the present study, two tumor suppressor genes, ADRP and FST were found to be upregulated in rat UCMSC, whereas these two genes were down regulated in human UCMSC when two types of UCMSC were co-cultured with corresponding species’ breast carcinoma cells." (PMID 25942583, 2015). "As activin displays an anti-proliferative effect in human mammary cells, the present findings indicate that an increased FST and FLRG expression in breast proliferative diseases might counteract the anti-proliferative effects of activin in human breast cancer." (PMID 19740438, 2009). "Our findings also highlight FST as a potential prognostic factor in HNSCC and that its negative effect on disease progression may result from a possible metastatic suppressor function as shown in breast cancer." (PMID 37492374, 2023). "In the bone tropic cells, NOG, FST and CHRDL1 are all positively regulated by ZEB1, whereas in different parental breast cancer cell lines only NOG and CHRDL1 are effectively targeted by ZEB1 and an antagonistic regulatory mechanism between NOG and FST seems to dominate and determine FST expression." (PMID 25973542, 2015). "Whereas we found that FST expression had no impact on tumor growth in the MMTV-Neu model, a previous report indicated that ectopic expression of FST decreased growth of R30C breast cancer xenografts compared with those overexpressing activin." (PMID 28583174, 2017).
Insulin resistance (22 papers, 2012 to 2025). Increased resistance towards insulin, that is, diminished effectiveness of insulin in reducing blood glucose levels. "In girls with PCOS, follistatin levels rise significantly after 6 months on OCs and this increase associates to a worsening of markers of insulin resistance and to changes in liver fat." (PMID 36843579, 2023). "In conclusion, in girls with PCOS, follistatin levels rise significantly after 6 months on OCs and this increase associates to a worsening of markers of insulin resistance and to the changes in ectopic fat depots, specifically in liver fat." (PMID 36843579, 2023). "Our findings suggest that GCKR regulates follistatin secretion and that elevated circulating follistatin associates with an increased risk of T2D by inducing adipose tissue insulin resistance." (PMID 34759311, 2021). "We also found that follistatin associated with adipose tissue insulin resistance and related traits, and that follistatin attenuated insulin-mediated suppression of lipolysis in adipocytes." (PMID 34759311, 2021). "In the MDC-CC cohort, we observed an association between the elevated follistatin and insulin resistance." (PMID 34759311, 2021). "In addition, studies with mice have shown that follistatin overexpression is associated with insulin resistance in WAT, elevated hepatic glucose production, and glucose intolerance." (PMID 33807959, 2021). "In conclusion, this study indicates that measurements of activin A, B, or follistatin cannot discriminate risk for T2D in individual patients, but nonetheless suggests that the activins and follistatin might have important roles in insulin resistance and the onset and development of T2D." (PMID 23304117, 2012). "Research has shown that follistatin acts as a pathological hepatokine that can be targeted for diabetes treatment in hepatic insulin resistance." (PMID 38793069, 2024). "Follistatin regulates muscle mass, glucose metabolism, and insulin resistance, and plasma levels of follistatin are increased by band resistance training, with greater increases produced by HIIT than with RT." (PMID 35757424, 2022). "Insulin resistance in hepatocytes compromises the inhibitory effect of insulin on follistatin and thus disrupts the ratio of glucagon-to-insulin, which controls follistatin synthesis." (PMID 35053214, 2022). "Here we investigated relationships of circulating follistatin with adipose tissue insulin resistance and related traits in humans." (PMID 34759311, 2021). "Many loci associated with adiponectin levels are shared with other insulin resistance traits and risk of type 2 diabetes, including loci near IRS1, LYPAL1, ARL15/FST, VEGFA, CMIP, and PEPD." (PMID 32915782, 2020). "Follistatin-overexpressing mice showed strong insulin resistance in WAT, increased hepatic glucose production, and glucose intolerance, which is in line with the higher levels observed in patients with T2DM." (PMID 32604889, 2020). "The significance was maintained after adjustment for weight loss or glucose but was lost after adjustment for insulin resistance (HOMA-IR) (Activin AB, p = 0.103 and follistatin p = 0.81, respectively)." (PMID 31672146, 2019). "This is also the first clinical study to measure activin B in glucose metabolism, whereas previous studies have examined activin A in glucose metabolism, and follistatin in insulin resistance." (PMID 23304117, 2012). "Specific outcomes of interest included clinical (e.g., menstrual regularity, ovulation rate, hirsutism), metabolic (e.g., BMI, insulin resistance, hepatic markers), hormonal (e.g., free testosterone, follistatin), and patient-reported outcomes such as quality of life." (PMID 40491634, 2025). "Another possible effect of FST overexpression on muscle is by improving insulin resistance which reinforces insulin’s action and increases insulin-stimulated intracellular insulin signaling of AKT/mTOR that increases protein synthesis and up-regulates muscle mass." (PMID 38409184, 2024).